IL6 (interleukin 6)
Diseases named in the same sentence as IL6 in open-access papers (continued):
Sharing a sentence is not in itself a finding about the gene and the disease.
liver dysfunction (40 papers, 2010 to 2026). "In Model 2, both of high IL6 (HR 2.5, [95% CI 1.1–5.4], p = 0.024) and higher (2b and 3) mALBI grade (HR 3.1, [95% CI 1.5–6.5], p = 0.003) were associated with liver dysfunction." (PMID 34080071, 2021). "Risk factors for liver dysfunction were high baseline IL6, albumin, and total bilirubin, and mALBI grade as found in univariate analysis." (PMID 34080071, 2021). "High baseline IL6 (HR 2.67 [1.21–5.94], p = 0.016) and total bilirubin ≥ 17 μmol/L (HR 3.73 [1.72–8.06], p < 0.001) were independently associated with liver dysfunction." (PMID 34080071, 2021). "Pretreatment liver injury was an independent poor prognostic factor in newly diagnosed DLBCL patients, correlating with increased serum levels of liver dysfunction-associated cytokines IL-2R, IL-6, IL-10, and TNF-α." (PMID 29109622, 2017). "Concentrations of IL-6 were associated with the severity of liver dysfunction, development of ALD complications, and turned out to be the only independent immune predictor of 90-day survival in the study cohort." (PMID 26107937, 2015). "In MCS-treated patients, liver dysfunction was shown to be associated to the progressive release of inflammatory mediators, such as interleukin-6 (IL-6), IL-8, and C-reactive protein (CRP)." (PMID 25132729, 2014). "In one study comparing immunoregulatory cytokines and the impact of Th17 regulatory T-cells in male and female ALD patients, elevated levels of IL-6 and Treg cells were associated with increased severity of liver dysfunction, development of complications, and decreased 90-day survival." (PMID 38370409, 2024). "Hepatic removal of IL-6 declines with increasing Child-Pugh score, and this may contribute to positive associations of systemic IL-6 levels and liver dysfunction." (PMID 28661458, 2017). "In addition to IL6, low albumin (HR 3.0, [95% CI 1.4–6.3]; p = 0.003), high total bilirubin values (HR 4.4, [95% CI 2.2–9.0]; p < 0.001), and higher mALBI grade (HR 3.9, [95% CI 1.9–8.1]; p < 0.001) were associated with shorter time-to-liver dysfunction." (PMID 34080071, 2021). "Furthermore, IL6 was independently associated with liver dysfunction in multivariate analysis." (PMID 34080071, 2021). "Among them, the hepatocyte growth factor (HGF), a potential surrogate of liver dysfunction, and the proinflammatory interleukins IL6 and IL15 were most profoundly altered." (PMID 40242314, 2025). "When interpreting CRP values, it is necessary to consider potential limitations (impairment of liver protein synthesis in severe hepatopathies and blocking of IL-6 during biological therapy—in both cases, CRP levels barely increase)." (PMID 38792824, 2024). "In some studies, IL-6 has been shown to be a more relevant prognostic factor in cases of severe systemic inflammation in patients with concomitant severe liver dysfunction than leukocyte count or CRP level." (PMID 37834802, 2023). "IL-6 levels correlate with liver dysfunction and influence hepatic biosynthesis via genetic processes with up- or downregulation of different components of the proteome, e.g., acute phase proteins." (PMID 36289602, 2022). "A recent study revealed that rapid and drastic elevation of serum IL‐6 was derived from circulating monocytes and ablation of monocyte‐derived IL‐6 in vivo alleviated liver dysfunction and systemic inflammation." (PMID 35548710, 2022). "Our results have shown that baseline IL6 values are independent prognostic factor for overall survival and liver dysfunction in advanced HCC patients who received RE combined with sorafenib." (PMID 34080071, 2021). "While in patients with high IL6, median time-to-liver dysfunction was 9.7 months; in patients with low IL6, it was 32.6 months." (PMID 34080071, 2021). "As we focused mainly on liver dysfunction, the mechanism proposed for liver dysfunction is inflammation; therefore, we measured a biomarker of proinflammatory process (IL-6)." (PMID 30991873, 2019).
liver dysfunction (continued). "The amount of proinflammatory cytokines including tumor necrosis factor (TNF)-α and interleukin (IL)-6 contribute to liver dysfunction." (PMID 30098593, 2018). "In the liver dysfunction group, patients had significantly higher level of IL-2R, IL-6, IL-10, and TNF-α, when compared with those in the normal liver function group." (PMID 29109622, 2017). "The correlation between IL-6 serum level and liver dysfunction was statistically significant on days 2, 5 and 10 with Spearman coefficients of -0.615 (d2; P = 0.001), -0.549 (d5; P = 0.004) and -0.674 (d10; P = 0.001), respectively." (PMID 28542386, 2017). "The onset of liver dysfunction is mainly determined by cytokines released by the tumor, such as IL-6 and TNFα, and it generally provokes fever, weight loss and an unfavorable prognosis." (PMID 28915665, 2017). "We also observed isolated over-expression of IL-6 increasing in parallel to the severity of liver dysfunction defined according to the criteria of the CTP and MELD." (PMID 26107937, 2015). "Higher levels of IL-6 are also observed in patients with PE, suggesting that placenta-derived IL-6 may be a candidate for a mediator of liver dysfunction." (PMID 41226773, 2025). "Interleukin‐1, IL‐6, IL‐18, interferon‐gamma, and TNF‐α play a key role in the pathogenesis of AOSD, and elevated IL‐1 and IL‐18 levels are closely associated with the systemic symptoms of AOSD, such as fever, rash, and liver dysfunction." (PMID 37397575, 2023). "In Model 1, multivariate analysis revealed that high IL6 (HR 2.67, [95% CI 1.21–5.94], p = 0.016) and high total bilirubin values (HR 3.73, [95% CI 1.72–8.06], p < 0.001) were independent prognostic factors of liver dysfunction." (PMID 34080071, 2021). "The same cutoff value for IL6 was also correlated with liver dysfunction." (PMID 34080071, 2021). "Furthermore, markers of liver dysfunction (albumin, total bilirubin, and INR) and inflammation (IL-6) were also associated with elevated levels of MGO." (PMID 34654829, 2021). "Firstly, the consequence of I/R injury include transient liver dysfunction and the systemic inflammatory response to syndrome, the indicators that reflected the systemic cytokines such as IL-6 or TNF levels in the sera from the blood samples of mice were not given." (PMID 30279567, 2018). "Of note, patients in the liver dysfunction group retained significantly higher levels of serum cytokines IL-2R, IL-6, IL-10, and TNF-α, compared with those in the matched control group (p = 0.003, p = 0.022, p = 0.045, and p < 0.001, resp.) and healthy volunteers (all p < 0.001)." (PMID 29109622, 2017). "But the second increase of TNF-α and IL-6 on day 10 in patients with severe liver dysfunction (group B) confirms this hypothesis." (PMID 28542386, 2017). "Liver dysfunction was evident through elevated biomarkers (AST, ALT, and TBIL) and pro-inflammatory IL-6, coupled with reduced anti-inflammatory IL-10." (PMID 40563258, 2025). "In this post hoc analysis, we sought to confirm the prognostic value of baseline cutoff values of 6.53 pg/mL and 60.8 pg/mL for IL6 and IL8, respectively, in overall survival (OS) or liver dysfunction (grade 2 bilirubin increase) after treatment." (PMID 34080071, 2021). "These two proteins (NF-κB and STAT3) are likely to play important roles in the liver inflammatory response and in the maintenance of homeostasis, induction of APP synthesis by stimulating cytokines such as IL-6 and TNF-α, and in inducing liver dysfunction." (PMID 23516407, 2013). "In this patient, serum IL18 levels correlated well with serum ferritin levels and the extent of liver dysfunction but dissociated with serum CRP and IL6 levels which had remained normal after initial high-dose corticosteroids and cyclosporine therapy." (PMID 24455384, 2013).
liver dysfunction (continued). "Interestingly, there were moderate correlations between fT3 and parameters of liver dysfunction (MELD: ρ = -0.448; p <0.001; and albumin: ρ = 0.434; p <0.001) and systemic inflammation (IL-6: ρ = -0.496; p <0.001; and CRP: ρ = -0.356; p <0.001)." (PMID 38125301, 2024). "One mechanism suggested for B19-induced hepatopathy include effects of the viral protein non-structural protein (NS) 1 through activation of interleukin-6 expression." (PMID 20727151, 2010).
neuromyelitis optica (40 papers, 2011 to 2025). A rare inflammatory disease of the central nervous system characterized mainly by attacks of uni- or bilateral optic neuritis (ON) and acute myelitis. "Cerebrospinal fluid (CSF) interleukin-6 (IL-6) can be markedly elevated in neuroinflammatory conditions, such as neuromyelitis optica spectrum disorder and myelin oligodendrocyte glycoprotein antibody-associated disease." (PMID 40175894, 2025). "Recently, two case series demonstrated that treatment with anti-IL-6R mAb has positive effects in neuromyelitis optica spectrum disorders in humans, further underlining the relevance of IL-6 in pathogenesis of CNS demyelinating disorders." (PMID 24155968, 2013). "Elevated production of the cytokines interleukin (IL)-6 or interferon (IFN)-α in the central nervous system (CNS) is implicated in the pathogenesis of neurological diseases such as neuromyelitis optica spectrum disorders or cerebral interferonopathies, respectively." (PMID 35429976, 2022). "Interestingly, CSF IL-6 concentration could help identify neuromyelitis optica spectrum disorder, myelin oligodendrocyte glycoprotein antibody-associated disease, and central nervous system (CNS) vasculitis." (PMID 35401550, 2022). "Elevations in IL‐6 have previously been identified in several immune‐mediated neurologic diseases, most notably neuromyelitis optica spectrum disorder (NMOSD), resulting in novel therapeutic strategies highly effective in controlling the disease." (PMID 40781580, 2025). "Modulation of interleukin‐6 (IL‐6) signaling affects the production of autoantibodies and suppresses disease activity in neuromyelitis optica, and a phase 3 trial with satralizumab in generalized MG is ongoing (NCT04963270)." (PMID 38321574, 2024). "Proinflammatory cytokines, such as (IL: interleukin) IL-6 and IL-17A, and complement fixation are critical in the immunopathogenesis of neuromyelitis optica spectrum disorders (NMOSD)." (PMID 38326464, 2024). "Patients diagnosed with neuromyelitis optica, primary progressive MS, and relapsing-remitting MS have also shown elevated IL-6 levels." (PMID 37629172, 2023). "Interleukin-6 not only induces acute phase reactions but also induces autoantibody production, such as anti-aquaporin 4 autoantibody production in neuromyelitis optica." (PMID 37025699, 2023). "Elevated levels of IL-6 in the CNS have been found in inflammatory CNS diseases, such as idiopathic transverse myelitis, and neuromyelitis optica, cancer, and cysts (median CSF IL-6 654.3 ± 247.9, 281, 22.87 ± 2.62, and 594.2 ± 191.8 pg/mL, respectively)." (PMID 35330399, 2022). "It has been shown that CSF interleukin (IL)-6 is increased in neuromyelitis optica spectrum disorders (NMOSD) or in myelin oligodendrocyte glycoprotein antibody-associated disease (MOGAD) compared to MS." (PMID 35401550, 2022). "The elevation of MMP-2 induced by IL-6 signaling was reported in the patients with BBB disruption of neuromyelitis optica." (PMID 29867440, 2018). "In humans, monoclonal antibodies directed against IL6 are used in several chronic inflammatory diseases, including initial trials in neuromyelitis optica." (PMID 27266518, 2016). "Satralizumab provides durable inhibition of IL-6 signaling and is indicated for another autoantibody-mediated neuroimmunological disease, aquaporin-4 immunoglobulin G antibody-positive neuromyelitis optica spectrum disorder, as monotherapy or as an add-on to immunosuppressive therapy (IST)." (PMID 39193150, 2024). "The neutralization of IL-6 could ameliorate neuromyelitis optica spectrum disorder and preserve the integrity of the BBB." (PMID 39291284, 2024). "For example, IL-6 is considered to be a key mediator of neuromyelitis optica." (PMID 35087475, 2021). "IL-6 is known to induce plasmablast production of anti-aquaporin 4 (Aqp-4) antibodies in vitro and may account for neuromyelitis optica (NMO) disease activity." (PMID 30415321, 2018).
neuromyelitis optica (continued). "IL-6 is increased in the CSF of other inflammatory neurological disorders including transverse myelitis (TM) and neuromyelitis optica (NMO), in the lesions of MS patients, and in some cases, correlates with relapse or general neurodegeneration in the progressive phase." (PMID 22096636, 2011). "IL-6 blockade was achieved by transferring neuromyelitis optica immunoglobulin G (NMO-IgG) autoantibodies and satralizumab through the BBB using a triple culture system, which mimics the close contact of endothelial cells, pericytes, and astrocyte processes." (PMID 40331982, 2025). "Within the context of neuromyelitis optica (NMOSD), in vitro and ex vivo BBB models demonstrated that blocking IL-6 suppressed the NMO-IgG-induced transmigration of T cells and barrier dysfunction." (PMID 37841263, 2023). "Moreover, IL-6 may promote the survival of the plasma blasts that secrete immunoglobulin or pathological autoantibodies, e.g., anti-aquaporin 4 in patients with neuromyelitis optica (NMO)." (PMID 31523783, 2019). "Certain peripheral proteins are involved in the development of Neuromyelitis optica spectrum disorders (NMOSD), such as IL-6, complement proteins, and MHC class II molecules." (PMID 40294019, 2025). "In neuromyelitis optica spectrum disorder (NMOSD), intrathecal IL-6 and GFAP are elevated during attacks." (PMID 40175894, 2025). "Anti-IL-6 therapeutics have recently been studied as a potential treatment for systemic sclerosis, SLE, and neuromyelitis optica (NMO)." (PMID 39062908, 2024). "In particular, increased CSF IL-6 levels have been reported in neuromyelitis optica in comparison to both RR-MS and other non-inflammatory neurological diseases." (PMID 32655367, 2020). "Increased levels of intrathecal IL-6 (albeit not the only cytokine elevated) have been found in various brain disease states ranging from traumatic brain injury, schizophrenia, depression, neuromyelitis optica spectrum disorder to Alzheimer’s and Lewy body dementia (LBD)." (PMID 37841263, 2023).
acute myeloid leukemia (39 papers, 2013 to 2026). Acute myeloid leukemia (AML) is a group of neoplasms arising from precursor cells committed to the myeloid cell-line differentiation. "The dysplastic phenotype in TRAF6-transduced mice is linked to IL-6 overexpression and paracrine action, while clonal expansion and acute myeloid leukemia (AML) development rely upon TRAF6 activation in a cell-autonomous fashion." (PMID 36428749, 2022). "The first study showed that elevated levels of interleukin-6 (IL-6) in patients with acute myelogenous leukemia or myelodysplastic syndrome were associated with poorer executive functioning before cancer treatment." (PMID 30442190, 2018). "High levels of the inflammatory cytokine IL-6 in the bone marrow are associated with poor outcomes in pediatric acute myeloid leukemia (pAML), but its etiology remains unknown." (PMID 36418348, 2022). "In vitro stimulation of peripheral blood mononuclear cells from acute myeloid leukemia patients induced substantial IL-6 release, and murine models have demonstrated that IL-6 mRNA expression parallels disease severity." (PMID 41439926, 2025). "For instance, CSF interleukin-6 has been reported to be a promising marker for the diagnosis of adult acute myeloid leukemia (AML) with CNS involvement." (PMID 40925373, 2025). "In particular, compared to healthy children and adolescents, pediatric patients with acute myeloid leukemia showed higher concentrations of IL-6 and TNFα." (PMID 35335997, 2022). "Reportedly, CXCR4 expression was concurrently increased with VEGF and IL-6 levels in stem cell chemoresistance of acute myeloid leukemia." (PMID 34070538, 2021). "For instance, among hematological malignancies we observed that IL6 was upregulated in large B-cell lymphoma while acute myeloid leukemia patients expressed lower levels of IL6 compared to healthy controls." (PMID 34576335, 2021). "IL-6 can be involved in regulating leukemic stem cell chemoresistance in acute myeloid leukemia (AML) via osteopontin (OPN) autocrine/paracrine signaling." (PMID 32872659, 2020). "In this context, elevated IL-6 and TNFα levels have been correlated with adverse survival in patients with acute myeloid leukemia (AML)." (PMID 28947904, 2017). "In addition, favorable prognostic indicators for survival in patients with acute myeloid leukemia (AML) include reduced levels of IL-6 and elevated levels of IL-10." (PMID 38337668, 2024). "Resveratrol also reduces IL-6-mediated Shh signal expression in acute myeloid leukemia." (PMID 23762150, 2013). "Thus, IL-8 could promote proliferation and resistance in acute myeloid leukemia cells, while IL-6 predicts survival rate and regulates the drug resistance in these cells." (PMID 38731966, 2024). "IL-6 also has a significant effect on hematopoiesis, especially for marrow suppression in the setting of acute myeloid leukemia (AML)." (PMID 33711076, 2021). "It is worth to mention that a few genes with a role in acute myeloid leukemia: GRB2, CSFIR, MARCKS and PDGFB were upregulated; FLT1, IL6, PIK3C2B, BALAP3 and MAPK10 were downregulated." (PMID 36413544, 2022). "mRNA expression levels of VEGFC (contrary to other VEGFs isoform), PI3K, AKT, mTOR, MEK1, PTEN,IL6, LC3 and P62 genes were upregulated in acute myeloid leukemia (AML) cells following treatment with ATO/THAL." (PMID 31721534, 2020). "In acute myeloid leukaemia, the FAK pathway regulates the expression of a number of cytokines (interleukin 6 (IL 6), IL 8, stromal cell-derived factor 1, and angiopoietin 1), which are crucial for CSCs maintenance." (PMID 29568377, 2018). "In our case series, IL-6 was highest in the nonsurviving infant with acute myeloid leukemia in whom a 10% increase of IL-6 after six hours of CS rescue therapy (started 86 h after PICU admission) was observed." (PMID 39518726, 2024). "Latrophilin-1 enhances IL-6 release through exocytosis in acute myeloid leukemia, but (importantly) not in healthy human leukocytes." (PMID 30332657, 2018).
acute myeloid leukemia (continued). "Elevated IL-6 in acute myeloid leukemia (AML) induces bone marrow failure and promotes myelodysplastic syndrome (MDS) to AML progression." (PMID 36809258, 2023). "A previous study suggests that acquired up-regulation of OPN-b and c isoforms might prevent conventional chemotherapy drug (Daunorubicin, Cytarabine and Idarubicin)-induced apoptosis in acute myeloid leukemia (AML) cells by upregulating the expression of AKT, VEGF, STAT3, CXCR4, and IL-6." (PMID 34359989, 2021). "Additionally, in vivo studies for acute myeloid leukemia (AML), cytokine release syndrome (CRS), and coxsackie virus B have suggested mir-146a as a potential therapeutic agent targeting the NF-kB-signaling pathway and the consecutive release of IL-1 and IL-6 inflammatory cytokines." (PMID 37109050, 2023).